CXCL10 (C-X-C motif chemokine ligand 10)
Diseases named in the same sentence as CXCL10 in open-access papers (continued):
Sharing a sentence is not in itself a finding about the gene and the disease.
lung carcinoma (continued). "A 2012 study demonstrates that CXCL10 attracts CXCR3-expressing tumor cells to the bone, though omitting its connection with lung cancer." (PMID 33262947, 2020). "Enhanced mRNA and protein levels of CXCL10, CCL5, and IFNβ were observed following silencing of NEAT1 in human and mouse lung cancer cells as measured by qRT-PCR and Western blot analysis, respectively." (PMID 32296457, 2020). "The combination of IL-12, IFN-γ, CXCL9 and CXCL10 has been shown to be strongly correlated with recruitment of CD8+ T cells in the tumor, in colorectal and lung cancers." (PMID 32033490, 2020). "A previous report demonstrated that the HDACi romidepsin enhances response to PD-1 blockade in lung cancer by inducing the expression of CCL5, CXCL9 and CXCL10, and thus enhancing T cells infiltration." (PMID 29371976, 2017). "Five altered cytokines in stage I lung cancer patients (CCL3, IL8, IL1β, CXCL10, sIL2Rα) were identified in plasma from subjects (n = 15) before and after resection using a 30-plex panel protein assay." (PMID 23762239, 2013). "Moreover, in “cold-type” lung cancer, epigenetic regulators can activate chemokines such as CXCL9 and CXCL10, transforming it into a “hot-type” tumor and significantly enhancing the response rate to PD-1/PD-L1 inhibitors." (PMID 41394878, 2025). "We had previously shown that the depletion of either CXCL9 or CXCL10 inhibits antitumor responses in murine lung cancer, underscoring nonredundant functions of these cytokines in cancer immunity." (PMID 38518770, 2024). "Therefore, IRF1 and STAT1 were knockdown in lung cancer A549 cells, which decreased 20 ng/mL of IFNα/γ-mediated gene expression, including IRF1, STAT1, PD-L1, CXCL10, and ISG15." (PMID 38953994, 2024). "We found that high levels of the 5 genes, PD-L1, ICAM-1, CXCL10, IRF1, and TAP1, were correlated with better survival probabilities in lung cancer patients treated with immunotherapies (N = 21, p = 0.17 for PD-L1, p = 0.28 for ICAM-1, p = 0.052 for CXCL10, p = 0.023 for IRF1, and p = 0.22 for TAP1)." (PMID 36688994, 2023). "For other genes, CXCL10 by probe 204533_at was correlated with a poor survival rate (p < 0.05) and IRF detected by probe 238725_at was correlated with a better survival probability in patients with lung cancer (p < 0.05)." (PMID 36688994, 2023). "CXCL10 was the only chemokine that did not decrease after TKI treatment in EGFR-TKI-sensitive EGFR-mutant lung cancer cell lines during coculture with activated PBMCs." (PMID 36612121, 2022). "CXCL10 (dot #4) was elevated in coculture supernatants derived from all the EGFR-mutant lung cancer lines (HCC4006, HCC827, and H1975) and did not decrease after EGFR-TKI treatment." (PMID 36612121, 2022). "Surprisingly, CXCL10 increased in EGFR-mutant lung cancer cell lines itself and did not decrease due to EGFR-TKI treatment." (PMID 36612121, 2022). "Taken together, the data suggest that healthy donor PBMCs increase their expression of CCL3, IL8 and IL1β (with little or no increases in CXCL10 and IL2Rα) when they are exposed to lung cancer cells (Figures 4and5)." (PMID 23762239, 2013). "Therefore, we concluded that SD70-induced KDM4C inhibition increases the CXCL10 transcriptional level to mediate the increased intratumoral infiltration and activation of CD8+ T cells, which in turn enhances the efficacy of our triple therapy in lung cancer." (PMID 35121645, 2022). "In addition, we found lower cell motility in the CD8+ T cells in the patients with lung cancer compared to in healthy CD8+ T cells (p < 0.05), and there were decreased levels of CXCL9 and CXCL10 in the patient’s nonCD8+ PBMCs compared to healthy nonCD8+ PBMCs (p < 0.05)." (PMID 34680466, 2021). "However, macrophages in lung cancer tissues expressed high levels of CXCL9 and CXCL10." (PMID 35069521, 2021).
lung carcinoma (continued). "Enhancement of paracrine CXCR3 ligands (CXCL9, CXCL-10, and CXCL-11) in the tumor microenvironment and deactivation of CXCR3 expression on cancer cells could be antitumorigenic by recruiting activated natural killer cells and T lymphocytes with potent antitumor effects in various lung cancer models." (PMID 36164329, 2022). "The serum levels of IFN-γ were not correlated with the serum levels of CXL9, CXCL10, and CXCL11, respectively, in all lung cancer and NSCLC patients." (PMID 34501934, 2021). "We speculated that increased IFN-γ during coculture with activated PBMC stimulated CXCL10 expression in EGFR-mutant lung cancer cell lines regardless of EGFR-TKI treatment; however, activated PBMC without coculture did not express CXCL10." (PMID 36612121, 2022). "Another study, which included 53 lung cancer patients, indicated that the subjects who developed irAEs possessed lower baseline levels of CXCL9, CXCL10, CXCL11 and CXCL19, as well as a greater increase in CXCL9 and CXCL10 at post-treatment, compared with those without irAEs." (PMID 36949956, 2023).
psoriasis (74 papers, 2009 to 2025). An autoimmune condition characterized by red, well-delineated plaques with silvery scales that are usually on the extensor surfaces and scalp. "This keratinocyte SPRY1/CXCL10/periarticular CD14hi macrophage/TNF-α axis provides valuable insights into the mechanisms underlying the transition from psoriasis to PsA and suggests potential therapeutic targets for preventing this progression." (PMID 40471688, 2025). "In active psoriatic plaques, CXCL10 production has been found from keratinocytes and dermal infiltrate, and the migration of NK cells toward CXCL10 has been implicated in psoriasis pathogenesis." (PMID 27964744, 2016). "It has been also recently demonstrated that over-expression of the chemokine ligand 10 (CXCL10), as was observed here with of SP-treated S. epidermidis, is clearly associated with psoriasis." (PMID 27148195, 2016). "This study identifies keratinocyte-derived CXCL10 and periarticular CD14hi macrophages as critical links in the skin-joint crosstalk leading to PsA and provides insights into the mechanisms underlying the transition from psoriasis to PsA." (PMID 40471688, 2025). "CXCL10 is suggested as a potential biomarker for psoriasis progression, but existing evidence is inadequate to confirm this, necessitating further validation." (PMID 40303401, 2025). "In recent years, the C-X-C motif chemokine 10 (CXCL10) has emerged as a biomarker for PsA development in psoriasis patients." (PMID 40284188, 2025). "The levels of markers associated with inflammation, namely IL-8, IL-6, CXCL10, and COX-2, were decreased in a psoriasis-like 3D reconstructed skin model by the effect of exosomes from mononuclear cells of human umbilical cord blood (UCB-MNC-sEV)." (PMID 40906403, 2025). "The expression of chemokines and their receptors are regulated by psoriasis-associated cytokines, including IL-17 which upregulates CCL2, CCL7, CCL20, and CXCL1, or IFN-γ which upregulates CXCL9 and CXCL10." (PMID 38642273, 2024). "Although several chemokines, such as CCL13, CXCL12, CXCL10, CCL27, and CCR6, have been identified in the context of psoriasis, CXCL10, in particular, has been suggested as a biomarker for psoriasis progression." (PMID 38829444, 2024). "IL-1β promotes the differentiation of Th17 cells to secrete IFN-γ, and IL-18 enhances IFN-γ-induced production of C-X-C motif chemokine 9 (CXCL9), CXCL10 and CXCL11, which migrate from dermis to epidermis causing chronic inflammatory activation of psoriasis." (PMID 39689159, 2024). "A number of serum analytes identified by Olink analysis, including PI3, IL-17C, CCL20, IL-20, IL-6, CXCL9, and CXCL10, have been previously identified as being elevated in serum samples of patients with psoriasis." (PMID 39224116, 2024). "CCL5 has been implicated in the progression of scleroderma, while IL-1β and CXCL10 have been proposed as biomarkers of disease progression in psoriasis." (PMID 37228128, 2023). "CXCL10 is a possible biomarker for the development of psoriatic arthritis among patients with psoriasis." (PMID 34829740, 2021). "Therapies frequently used in psoriasis patients such as dimethylfumarate or apremilast can inhibit chemokines like Cxcl9 and Cxcl10, which highlights the role of these two chemokines in psoriasis." (PMID 34440590, 2021). "Studies have shown that IFN-γ, Th1 cytokines, CXCL10, IL-23, and Th17 are involved in the pathogenesis of psoriasis." (PMID 34630818, 2021). "The results of this study showed that CXCL10 was the potential gene target of the drugs for treating psoriasis." (PMID 32669126, 2020). "CXCL8 and CXCL10 expressions have been reported to increase in the lesional skin from patients with psoriasis." (PMID 33149756, 2020). "CXCL10 has been reported to be expressed in many Th1-type human inflammatory diseases, including skin diseases (e.g. psoriasis)." (PMID 32669126, 2020).
psoriasis (continued). "It has been found that INF-gamma and Th1 cytokines/chemokines, importantly C-X-C motif chemokine 10 (CXCL10), IL-23, and Th17 are involved in the pathogenesis of psoriasis and psoriatic arthritis." (PMID 31157131, 2019). "These include the chemokine Cxcl9 and Cxcl10 genes as typical molecular LP markers that distinguish lichenoid tissue reactions from atopic dermatitis and psoriasis." (PMID 31447864, 2019). "Of the five genes (BATF2, HRNR, SIGLEC1, SLC4A11, CXCL10) uniquely identified by multiDE (with Bonferroni adjustment), four were found to be closely related to psoriasis." (PMID 27334001, 2016). "In serum from patients with PsA and psoriasis, CXCL10 expression has been reported as either elevated or unchanged compared with that of control subjects." (PMID 27964744, 2016). "Previously, chemokine (C-X-C motif) ligand 10 (CXCL10) was identified as a predictive biomarker of PsA in patients with psoriasis and was reduced after development of PsA." (PMID 27964744, 2016). "We have also previously shown that serum levels of CXCL10 were elevated in patients with psoriasis who subsequently developed PsA compared with those who did not develop PsA, and this was independent of clinical predictors of PsA." (PMID 27964744, 2016). "Serum CXCL10 levels are negatively correlated to PsA duration and elevated in patients with psoriasis prior to development of PsA, but they drop after PsA onset." (PMID 27964744, 2016). "Transfection of ECs with psoriasis-associated CARD14 mutations resulted in increased expression of several chemokines, including IL-8, CCL2, and CXCL10." (PMID 25369198, 2014). "These periadnexal areas also contained higher expression of TIA-1, CXCR3, and CXCL10 in DLE versus psoriasis lesional skin." (PMID 24744689, 2014). "Transfection of dermal ECs with psoriasis-associated CARD14 mutations resulted in increased expression of several chemokines, including CXCL10, IL-8, and CCL2." (PMID 25369198, 2014). "CXCL10 is a widely reported biomarker for PsA and could predict future PsA development in patients with psoriasis." (PMID 40471688, 2025). "CXCL10 has been found elevated in the serum and synovial fluid of patients with PsA, and it is known to predict the future development of PsA in patients with psoriasis." (PMID 40471688, 2025). "Interestingly, a role for CXCL10 in psoriasis pathogenesis has been proposed and CXCL10 levels in patient serum has been suggested as a potential biomarker of disease severity." (PMID 40121229, 2025). "However, the cellular and molecular mechanisms by which CXCL10 contributes to the pathogenesis of PsA, especially the transition from psoriasis to PsA, remain incompletely understood." (PMID 40471688, 2025). "It has been suggested that CXCL10 may be involved in the pathogenesis of PsA and is considered a predictive biomarker for psoriasis." (PMID 40540498, 2025). "Moreover, mediators secreted by γδ T cells activate KCs to produce multiple psoriasis-associated mediators, including NF-α, IL-6, CXCL9, CXCL10, and AMPs." (PMID 38642273, 2024). "Previous reports have shown that CXCL10 expression increases in the plasma of psoriasis patients and may be a significant factor in psoriatic arthritis development." (PMID 34220863, 2021). "One hypothesis could be that the psoriasis patient group with a high level of CXCL10 is more prone to develop arthritis due to its chemoattractant properties on CXCR3+ CD4+ and CD8+ T cells." (PMID 34127053, 2021). "Oral administration of genistein in psoriasis patients for 8 weeks impaired the transcription of genes overexpressed in psoriasis, CXCL10, IL-6, STAT3, NFKB1, CCL4 while stimulated the transcription of gene repressed in psoriasis, IL-1RN in peripheral blood cells or lesional skin." (PMID 32751360, 2020).
psoriasis (continued). "A recent study suggested that the decrease in serum CXCL10 level over time was related to the new onset of psoriatic arthritis in patients with psoriasis, and our study revealed a same result that CXCL10 was up-regulated in psoriasis." (PMID 32669126, 2020). "Our findings may also be applicable to other itch disorders where neutrophil chemoattractants and/or CXCL10 are also elevated, such as psoriasis and allergic contact dermatitis." (PMID 31631836, 2019). "In our study, CXCL10 upregulation in psoriatic skin may indicate enhanced IFN-signalling in psoriasis, and therapeutic IFNAR removal has proven to be effective in psoriatic skin inflammation treatment by UV phototherapy." (PMID 28790368, 2017). "Importantly, in a mouse model of psoriasis, p204 knockdown improved epidermal hyperplasia, alleviated skin inflammation and reduced the expression levels of CXCL10 and CCL20." (PMID 27137868, 2016). "Attenuation of CXCL10 levels is a consequence of therapies currently approved for the treatment of psoriasis and PsA, such as the phosphodiesterase-4 inhibitor apremilast and the TNFα inhibitor etanercept, further supporting a role for CXCL10 in the pathogenesis of PsA." (PMID 27964744, 2016). "Thus, we compared expression of T cell, B cell, and macrophage markers and their associated proteins, TIA-1, CXCR3, and CXCL10 in DLE lesional skin, psoriasis lesional skin, and normal skin." (PMID 24744689, 2014). "Several of the chemokines that were determined to be upregulated by psoriasis-associated CARD14 mutations in ECs, have been found by previous gene array studies that LS skin contains significantly higher expression of IL-8, CXCL1, and CXCL10 than does NL skin." (PMID 25369198, 2014). "Additionally, HDBECs cultured with IL-17, TNFα, and IFNγ, three cytokines heavily implicated in psoriasis pathogenesis, resulted in upregulation of IL-8, CXCL1, CXCL10, and CCL5." (PMID 25369198, 2014). "An increased cebpb expression, epidermal thickness, infiltration of dendritic cells, and γδ T cells as well as the expression of pro-inflammatory cytokines (IL-6, IL-23, and IL-17) and chemokines (CCL5 and CXCL10) could have contributed to this increase in psoriasis severity." (PMID 35663991, 2022). "Thus, CXCL10 may be important in the pathogenesis of PsA and may be a useful predictor of PsA in patients with psoriasis." (PMID 27964744, 2016). "We ascertained that CXCL10 levels were elevated in the serum and lesional epidermis of patients with psoriasis (GEO GSE166388), and CXCL10 was more significantly upregulated in the lesional skin of PsA compared with psoriasis (GEO GSE205748 and GSE186063)." (PMID 40471688, 2025). "Multiple chemokines have higher expression levels within the lesion-prone skin of psoriasis sufferers, including the CXC chemokine family members CXCL9, CXCL10, and CXCL11, with increased expression of CXCL9/10 being characteristic of psoriasis." (PMID 40303401, 2025). "This study explores the regulatory roles and mechanisms of chemokines CXCL9, CXCL10, and CXCL11 in psoriasis." (PMID 40303401, 2025). "Proteins related to the central disease‐driving pathways of psoriasis, namely the TH1 (CCL3, CCL4, CXCL9, CXCL10, CXCL11, TNFα) and TH17 pathway (CXCL1, CCL20, IL‐17A, IL‐12B) were found elevated in lesional skin across both studies." (PMID 40970551, 2025). "CXCL10 and CXCR3 were found in keratinocytes and dermal infiltrates from active psoriasis plaques, and psoriasis patients had higher serum levels of CXCL1052." (PMID 38321132, 2024). "HS and psoriasis samples had 17 upregulated proteins in common, including interleukin (IL)–6, IL2 receptor α (IL2RA), IL17A, C-X-C motif chemokine ligand 10 (CXCL10), and CD177." (PMID 37108348, 2023). "In the current study, the levels of IL-6, IP-10/CXCL10, MIP-3α/CCL20, and ICAM-1 were upregulated in M5-stimulated HaCaT cells (in vitro model of psoriasis)." (PMID 35209199, 2022).